INS (insulin)
Diseases named in the same sentence as INS in open-access papers (continued):
Sharing a sentence is not in itself a finding about the gene and the disease.
vitamin D deficiency (continued). "Vitamin D deficiency is correlated with mUFC and mUFC values>240 nmol/24 h are associated with hypovitaminosis D. The supplementation of cholecalciferol had a positive impact on insulin sensitivity and lipids." (PMID 36313775, 2022). "Vitamin D deficiency is correlated with mUFC and values of mUFC > 240 nmol/24 h are associated with hypovitaminosis D. Cholecalciferol supplementation had a positive impact on insulin sensitivity and lipids." (PMID 35267948, 2022). "In the end, vitamin D deficiency causes impaired insulin sensitivity and immune system." (PMID 35267948, 2022). "However, in a population from Bangladesh at high risk of T2D, the ApaI polymorphism was associated with insulin secretion and a higher prevalence of vitamin D deficiency." (PMID 35956323, 2022). "It has been suggested by other interventional studies that vitamin D supplementation might enhance the secretion and sensitivity of insulin in patients with vitamin D deficiency, thus causing significant beneficial effects on the CVD risk biomarkers." (PMID 36193546, 2022). "Furthermore, it has been noted that vitamin D is involved in the regulation of glucose homeostasis by stimulating insulin synthesis and its secretion and that in cases of vitamin D deficiency the insulin secretion is altered." (PMID 35087418, 2021). "Furthermore, vitamin D deficiency has been associated with impaired insulin sensitivity, whereas vitamin D replacement in deficient individuals has been shown to improve insulin sensitivity." (PMID 33567588, 2021). "The majority of those studies have concluded that the link between vitamin D and DM as well as its complications is mainly because vitamin D deficiency contributes to their key pathological processes through multiple mechanisms such as enhancement of insulin resistance and β-cell death." (PMID 34722576, 2021). "Vitamin D receptors are known to exist in pancreatic tissue, and calcium plays an essential role in B-cell insulin secretion, which implies that Vitamin D deficiency could increase the risk of impaired glucose metabolism." (PMID 32024097, 2020). "Therefore, vitamin D deficiency affects insulin secretion, peripheral responses to insulin, and immune system function, which can result in insulin resistance and other inflammatory processes contributing to glucose and fat metabolism disorders." (PMID 32435279, 2020). "Patients with DKA who are at risk for hypophosphatemia include those with low blood pH, extremely high blood glucose level and very low BE, nil by mouth patients who have received intravenous insulin for longer than 24 h, cachectic or malnourished patients, and those with a vitamin D deficiency." (PMID 30940174, 2019). "Pregnant women in AMA with vitamin D deficiency have higher fasting insulin (14.70(8.76–34.65) and 10.89(7.15–16.12), respectively, P = 0.031) and HOMA-IR indices (1.78(1.07–4.14) and 1.30(0.83–1.89), respectively, P = 0.024) than those with vitamin D non-deficiency." (PMID 31849339, 2019). "Furthermore, vitamin D supplementation has been shown to reverse the defects in insulin secretion observed in mice and rabbits with vitamin D deficiency." (PMID 31514368, 2019). "Vitamin D deficiency is involved in the impairment of insulin synthesis and secretion and may be considered as an environmental factor with a pivotal role in the pathogenesis of T1D." (PMID 31823791, 2019). "Besides Akt phosphorylation eNOS phosphorylation was also unaltered by testosterone treatment or vitamin D deficiency, suggesting unchanged insulin signaling." (PMID 31509973, 2019). "It has been also observed that vitamin D deficiency contributes to increasing Ca2+ concentration that may decrease GLUT-4 activity leading to insulin resistance." (PMID 30959886, 2019). "Serum testing revealed vitamin D deficiency and elevated levels of insulin and triglycerides." (PMID 29651419, 2018).
vitamin D deficiency (continued). "There was statistically significant inverse association between vitamin D level and fasting blood glucose and with HbA1c among both vitamin D deficient and nondeficient women but there was a positive association between vitamin D deficiency and fasting insulin." (PMID 29808168, 2018). "Vitamin D deficiency is known to impair the release and action of insulin." (PMID 29710852, 2018). "Consistently, in other studies it has been reported that patients with T1DM displayed vitamin D deficiency, and that insulin gene expression in pancreatic β-cells may also be modulated by vitamin D." (PMID 30250851, 2018). "Therefore, vitamin D deficiency is related to blood glucose and insulin concentration alterations as well as target tissue sensitivity to insulin." (PMID 29449829, 2018). "In animal experimental studies, vitamin D deficiency inhibits pancreatic secretion of insulin and vitamin D repletion of rats with vitamin D insufficiency has been shown to improve glucose tolerance and glucose-stimulated insulin release." (PMID 28686645, 2017). "Similarly, vitamin D receptor knockout or vitamin D deficiency impairs glucose induced insulin secretion whereas insulin secretory response improves after vitamin D supplementation in both animals and humans." (PMID 28423063, 2017). "Interestingly, vitamin D deficiency alone caused a similar increase in fat accumulation within the liver, while also causing a mild decrease in insulin sensitivity." (PMID 28880231, 2017). "Moreover, hypocalcemia worsens effects of vitamin D deficiency, including decreasing further the glucose-stimulated release of insulin from β-cells." (PMID 27413370, 2016). "Inadequate insulin secretion has been identified in rodents with vitamin D deficiency." (PMID 27221615, 2016). "Underlying mechanisms might include a decreased insulin sensitivity related with increased parathyroid hormone levels which, in turn, are associated with vitamin D deficiency." (PMID 26873590, 2016). "In support to this finding, an intriguing correlation between vitamin D deficiency and type 1 diabetes has been observed, which may be due to the ability of vitamin D to preserve insulin release modulating the extracellular and intracellular calcium pools." (PMID 23671861, 2013). "Also the prevalence of vitamin D deficiency in women with T2DM is more common and also,old men with vitamin D deficiency, secret higher insulin after glucose intake." (PMID 23443033, 2013). "Vitamin D deficiency may influence its effects on insulin secretion and sensitivity via its effects on intracellular calcium." (PMID 20011094, 2010). "Longitudinal studies with serial measurements of maternal plasma 25-[OH] D concentrations, indices of insulin sensitivity and secretion are needed to elucidate the mechanisms and patho-physiological consequences of maternal vitamin D deficiency during pregnancy." (PMID 19015731, 2008). "Vitamin D deficiency during pregnancy may impact insulin secretion." (PMID 39749014, 2024). "Therefore, vitamin D deficiency causing an alteration in calcium flux could interfere with normal insulin secretion." (PMID 37895163, 2023). "In this study, ultrasonic BMD measurement and the detection of bone metabolism indexes such as Vitamin-D were carried out on patients with GDM to investigate whether Vitamin-D deficiency affects blood glucose and insulin levels, aiming to explore whether GDM has an impact on bone metabolism and BMD." (PMID 35634591, 2022). "Besides this, the inflammation may be in association with acidosis, vitamin D deficiency, and uremic toxins, which decreased insulin sensitivity, leading to subsequent muscle wasting." (PMID 34150871, 2021). "Vitamin D deficiency may compromise the ability of β cells to convert proinsulin to insulin." (PMID 34684492, 2021). "Interestingly, vitamin D deficiency alone was sufficient to decrease insulin sensitivity." (PMID 28880231, 2017).
vitamin D deficiency (continued). "Previous reports suggest that vitamin D deficiency may influence glucose homeostasis through increased intracellular calcium leading to aberrant insulin signaling and attenuation of downstream insulin signaling enzymes such as glycogen synthase and the glucose transporter 4 (GLUT 4)." (PMID 27754361, 2016). "Interventions investigating whether vitamin D supplementation can also enhance exercise-induced improvements in metabolic health are necessary in overweight women with PCOS, who demonstrate increased risk for vitamin D deficiency, and who are inherently insulin resistant." (PMID 27916865, 2016). "A recent meta-analysis revealed that vitamin D intervention improves FBG, HbA1c, insulin levels, and HOMA-IR in patients with T2DM, particularly among those with baseline vitamin D deficiency." (PMID 40692600, 2025). "Vitamin D levels were inversely correlated with insulin and HOMA-IR, and women with lower vitamin D levels exhibited higher PCSK9 concentrations, suggesting a potential link between vitamin D deficiency and metabolic dysregulation." (PMID 41516208, 2025). "Vitamin D corrects vitamin D deficiency in T2DM by supporting and modulating insulin production and secretion through several mechanisms." (PMID 40806075, 2025). "Overall, vitamin D deficiency in pregnancy has been consistently associated with an elevated risk of GDM, and vitamin D supplementation shows potential benefits for improving insulin sensitivity and glycemic control during gestation." (PMID 40863099, 2025). "Vitamin D deficiency is linked to an increased risk of developing T2DM, possibly due to its impact on glucose metabolism through β-cell function and insulin sensitivity." (PMID 38741878, 2024). "Vitamin D insufficiency leads to decreased insulin, and this condition will activate the lipogenesis mechanism, which will indirectly increase the fat mass." (PMID 37242192, 2023). "Additionally, vitamin D insufficiency may be linked to decreased insulin emissions in T2DM." (PMID 36833019, 2023). "Previous studies have also reported that vitamin D deficiency is a risk factor for GDM and that vitamin D directly influences pancreatic β-cells and is required for optimal insulin secretion." (PMID 37836571, 2023). "Studies proved that vitamin D deficiency is associated with a higher incidence of T2DM and vitamin D supplementation can dramatically increase insulin sensitivity in people with IR and vitamin D deficiency." (PMID 37895163, 2023). "Several theories propose linking vitamin D deficiency and PCOS including the fact that Vitamin D improves insulin action by upregulating the expression of the insulin receptor and enhancing insulin responsiveness for glucose transport." (PMID 35566720, 2022). "Vitamin D deficiency has been associated with the most prevalent phenomena in PCOS, such as hyperandrogenism, insulin resistance, adiposity indices, systemic proinflammatory indices, and ovulatory dysfunction." (PMID 34684492, 2021). "Increased BMI and WHR, high levels of fasting insulin, HOMA-IR, total cholesterol, LDL-C and hs-CRP were regarded as risk factors, but high level of HDL-C was considered to be protective factor of vitamin D deficiency in PCOS women." (PMID 32296394, 2020). "The FokI (rs10735810) polymorphism of the VDR gene was found to be an additional independent determinant of insulin secretion in individuals with vitamin D insufficiency." (PMID 32407388, 2020). "Replacement therapy with vitamin D has increased insulin sensitivity and reduced androgen levels in PCOS patients with vitamin D deficiency in a number of studies." (PMID 34394253, 2020). "Participants with vitamin D deficiency or inadequacy had higher levels of SBP, insulin, and HOMA-IR than those with vitamin D adequacy (p<0.05)." (PMID 32071197, 2020). "In vivo studies found that vitamin D deficiency and VDR knockdown reduce the secretion of insulin from pancreatic β-cells." (PMID 32149047, 2020).
vitamin D deficiency (continued). "A 6-week vitamin D-deficient diet induced a vitamin D insufficiency in rats (serum 25-OHVD3 levels: <20 ng/ml) combined with significant changes in serum levels of irisin, Ca, insulin, and glucose." (PMID 32082189, 2020). "Vitamin D insufficiency also leads to elevated parathyroid hormone concentrations, decreased insulin sensitivity, activated lipogenesis, and an increase in fat mass." (PMID 30881343, 2019). "Fasting glucose, glycated hemoglobin (HbA1c), 25OHD levels and daily insulin requirement were evaluated and Cholecalciferol 1000 IU/day supplementation for the management of vitamin D insufficiency (<75 nmol/L) was systematically added." (PMID 27607348, 2016). "Despite correction of vitamin D deficiency, there were no statistically significant between-group differences at 24 weeks in insulin resistance, fasting blood glucose, plasma insulin, HbA1c, body mass index, or lipid profile." (PMID 42266269, 2026). "The vitamin D receptor (VDR) and the 1-alpha-hydroxylase-converting enzyme expressed in pancreatic beta cells suggests a direct impact on insulin secretion, where vitamin D insufficiency could interfere with normal insulin release by altering calcium flux." (PMID 40869611, 2025). "Although only insulin was classified as moderate in the evaluation, our results still provide appropriate recommendations on Vitamin D supplementation for T2DM patients, especially for those with Vitamin D deficiency." (PMID 39525505, 2024). "The impact of the particular combination of variables (age, gender, BMI-SDS, vitamin D deficiency, vitamin D seasonality, 25(OH) D, serotonin, T-Chol, LDL-C, HDL-C, TAG, Glu, insulin, HOMA) on SBP-SDS, DBP-SDS and the BP classification was further investigated using the SPSS decision tree." (PMID 35581625, 2022). "Literature suggests that replenishing serum vitamin D may help to improve secretion of insulin and treat glycemia in DMT2 patients with concomitant vitamin D deficiency." (PMID 35340511, 2022). "Furthermore, they proposed that vitamin D deficiency could lead to enhance fatty acid β-oxidation and increases the adipose tissue energy expenditure, which might result in the overall reduction in body weight, increased plasma insulin levels, and increased hepatic lipid accumulation." (PMID 35859985, 2022). "Apart from these, vitamin D deficiency could also lead to elevated levels of parathyroid hormone (PTH), which has been documented to reduce insulin-stimulated glucose uptake." (PMID 35859985, 2022). "Maternal vitamin D deficiency has been associated with an elevated risk of GDM, and supplementation can improve glucose haemostasis by lowering fasting blood glucose, HbA1c, and serum insulin concentration." (PMID 35464031, 2022). "By way of conclusion, Vitamin D deficiency has negative impact on glucose, insulin, and HOMA-IR levels in obese children and adolescents." (PMID 36199866, 2022). "Furthermore, a decrease in glucose, insulin, and HOMA-IR levels was identified after Vitamin D3 supplementation of patients with Vitamin D deficiency." (PMID 36199866, 2022). "In a mouse study, maternal vitamin D deficiency induced structural remodeling of the pancreas and impaired insulin secretion due to reduced gene expression of PDX-1, which regulates the expression of GLUT2, glucokinase, and insulin in adult offspring." (PMID 34209784, 2021). "A variety of factors can affect the relationship between muscle quality and BMD, including vitamin D deficiency, testosterone, estrogen, and insulin growth factors, none of which are independent variables." (PMID 34948767, 2021). "Subjects with Vitamin D deficiency have significantly high values (p < 0.05) for BMI z-score, waist circumference, waist z-score, body fat percentage, FMI, systolic and diastolic BP, total cholesterol, triglycerides, LDL-C, insulin, HOMA-IR, leptin, and PTH." (PMID 32024097, 2020).
vitamin D deficiency (continued). "Moreover, the insulin gene is transcriptionally regulated by VDR in pancreatic β cells, and vitamin D deficiency reduces insulin secretory response to carbohydrate loading in experimental models." (PMID 33126575, 2020). "For example, high-dose vitamin D supplementation has shown convincing benefits for insulin sensitivity in pre-diabetic subjects, PLWH with vitamin D deficiency and insufficiency may require timely vitamin D supplementation." (PMID 33329379, 2020). "Low levels of insulin are seen in mice with either vitamin D deficiency or non-functioning vitamin D receptors." (PMID 31259115, 2019). "In the current study, women with vitamin D deficiency have higher fasting insulin concentration than those with vitamin D non-deficiency." (PMID 31849339, 2019). "However, vitamin D deficiency significantly associated with FBG, HbA1c, and insulin in the postmenopausal women." (PMID 29808168, 2018). "Interestingly, glucose-stimulated insulin response experiments suggest that early vitamin D supplementation may be protective of insulin secretory function, whereas late supplementation, after vitamin D deficiency and T2DM have been established, may be relatively ineffective." (PMID 26959059, 2016). "Another study on 126 healthy people showed that there is a direct relation between insulin sensitivity and 25(OH)D level and that vitamin D deficiency had a negative effect on β-cell function in pancreatic β-cells." (PMID 23443033, 2013). "In contrast to our result, in a study performed with 33 non-diabetics vitamin D deficient patients, two oral doses of 100,000 IU cholecalciferol corrected the vitamin D deficiency after two weeks without affecting on the glucose or insulin levels." (PMID 23351271, 2012). "There are some reports suggesting that vitamin D deficiency has a negative effect on insulin sensitivity and that it increases type 2 diabetes prevalence in adults." (PMID 22155459, 2011). "Vitamin D deficiency causes a reduction in insulin secretion without altering glucagon secretion." (PMID 34070202, 2021). "It has been proven that insulin relaxation is not altered in male coronary vessels due to vitamin D deficiency, while in vitamin-D-deficient females, insulin-induced relaxation is significantly decreased both in small coronary segments and in large, aortic rings." (PMID 34066967, 2021). "Furthermore, the data from logistic regression model of risk factors for vitamin D deficiency revealed that increased BMI and WHR, high levels of fasting insulin, HOMA-IR, total cholesterol, LDL-C, and hs-CRP were regarded as risk factors of vitamin D deficiency in PCOS women." (PMID 32296394, 2020). "Interestingly, vitamin D insufficiency is also connected with elevated infiltration of fat in skeletal muscle that appears independently of body mass and seems to contribute to decreased action of insulin." (PMID 30959886, 2019). "Moreover, Chinese individuals with vitamin D deficiency have higher fasting insulin and HOMA-IR compared to those with vitamin D non-deficiency." (PMID 31849339, 2019). "This suggests that vitamin D deficiency may be specifically associated with hepatic lipid accumulation and hepatic insulin resistance regardless of visceral fat accumulation, although the mechanism cannot be determined from the present study." (PMID 24130687, 2013). "However, prevalence of vitamin D deficiency in children with T1D and its effects on metabolic control, insulin requirement and lipid levels have not yet been fully clarified." (PMID 22155459, 2011). "However, these associations, as well as the relationships between severity and/or duration of vitamin D deficiency and insulin sensitivity, are issues which are not clear and which require further documentation." (PMID 22155462, 2011).